IFI27 (interferon alpha inducible protein 27)
Diseases named in the same sentence as IFI27 in open-access papers (continued):
Sharing a sentence is not in itself a finding about the gene and the disease.
tumor (continued). "Our study suggests that ATF3 plays an anti-tumor function in TSCCs through the negative regulation of its downstream targets, IFI6 and IFI27." (PMID 33539340, 2021). "Taken together, these results suggest that ATF3 negatively modulates TSCC tumor growth and differentiation in vivo through the expression level of IFI6 or IFI27." (PMID 33539340, 2021). "Methylation inactivation of tumor suppressors such as UCHL1 and TUSC3 were diagnosed with EOC.IFI27 was responsible for the proliferation of epithelial cancer cells.Li IFI27 was associated with invasion and drug resistance in EOC." (PMID 30970615, 2019). "Several of these genes, including IFI27, IFITM1, IRF1, STAT1, IF16, and TAP1, are known to possess potent anti-proliferative and tumor suppressive properties." (PMID 29176033, 2017). "Among the top dysregulated genes when comparing control and tumor free tissue were those involved in apoptosis (CIDEC, MUC1, ZBTB16, PRNP, ECT2), immune response (IFI27) and differentiation (KRT36)." (PMID 28038473, 2017). "An interferon gene signature was also present in the profiles derived from the tumor epithelium of the ER-positive tumors (e.g., STAT1, IFIT1, IFIH1, IFI27, ISG15, OAS1, OAS3, OASL) and ER-negative tumors (e.g., HLA-DQA1 and HLA-DQB1)." (PMID 19225562, 2009). "In addition to IGFBP7, the remaining differential genes (SDC2, COL8A1, IFI27, and ALDH1A1) were related to tumor drug resistance in the intersection of drug resistance differential genes." (PMID 40224214, 2025). "Similarly, cells in immune_2 and immune_1, which are surrounded by tumor and stroma, respectively, have distinct expression patterns of marker genes such as ISG15, IFI6, and IFI27." (PMID 39960663, 2025). "Additionally, three genes (PRDM1, IFI27 and SIGLEC15) were highly expressed in tumor tissues but were also favorable prognostic factors, suggesting a paradox: they promote carcinogenesis but inhibit tumor progression." (PMID 38287330, 2024). "Gene expression mRNA level analysis exhibited significant upregulation of mRNA levels in tumor tissue: IFNAR1 (3.4-fold increase, p < 0.0001), IRF9 (4.2-fold increase, p < 0.0001), STAT1 (7.1-fold increase, p < 0.0001), and IFI27 (66.3-fold increase, p < 0.0001)." (PMID 39457004, 2024). "The detailed mechanisms of IFI6 and IFI27 regulating tumor growth however have not been well elucidated." (PMID 36210388, 2022). "Downregulation of IFI27 expression might be partially involved in tomatidine- and TRTLE-induced inhibition of 85As2 cancer cell proliferation and tumor growth." (PMID 35267998, 2022). "We found that the IFI27 immunohistochemistry score was positively correlated with PABPC1, with approximately 78.3% of tumor tissues (83/106) with high IFI27 expression showing high PABPC1 staining, and 59.5% (50/84) of those with low IFI27 expression displaying low PABPC1 staining." (PMID 35346324, 2022). "Furthermore, we identified potential molecular targets based on our expression data in NE-low and immune-oasis tumor subsets, including CD70, ANXA1, ITGB6, TP63, IFI27, YBX3 and CXCR2." (PMID 34200100, 2021). "To validate the biological role of ATF3 in TSCCs through IFI6 and IFI27 in vivo, we first tested whether the inhibition of ATF3 promotes tumor growth of TSCCs in mice." (PMID 33539340, 2021). "As expected, IFI27 could revert the promotion of migration and invasion induced by RCAN1.4 knockdown in PDAC tumor cells." (PMID 33824473, 2021). "Therefore we conclude that ATF3 plays an anti-tumor function in TSCCs likely through the negative regulation of expression of its downstream targets IFI6 and IFI27." (PMID 33539340, 2021). "However, such genes as IFI27 (−4.38), SLC22A7 (−3.97), IFIT1 (−3.91), TGFB3 (−3.71), and IFN-α induced (−3.72) also had stronger suppression at the transcript level in HCC-R tumor tissues." (PMID 24377043, 2013).
tumor (continued). "IFI27 is transcribed as a type I interferon (IFN-I) stimulated gene (ISG) mediated by the STAT1/STAT2/IRF9 complex, and activation of the interferon-alpha receptor and increased mRNA levels of ligands and receptors in the TGFB pathway play important roles in the PDAC tumor microenvironment." (PMID 41008826, 2025). "Likewise, interferon response genes (including TLR3, MX1, RSAD2, IFI44, IFI27, IFIT1, and IFIT3), and chemokine genes (including CCL7, CXCL10, CXCR1, and CCL25) were significantly increased in PM-treated MM tumor tissues, whereas panobinostat showed minimal effects at equivalent doses." (PMID 40562746, 2025). "MARCO was found to be co-regulated with IFI27 expression and exhibited a similar parameter profile for the multivariate Cox proportional hazards model, suggesting that the detection of MARCO in tumor tissue would limit the impact of TGFB2 knockdown for OS improvements in PDAC patients." (PMID 39457004, 2024). "Macrophage in this cluster had high expression of type I interferon signaling related genes (IFITM3, IFI27, MX1, IFI6, and ISG15) as well as gene features related to immunosuppressive phenotype (APOE, APOC1, S100A9, and GPNMB), whereby participating in tumor immune regulation." (PMID 35265520, 2022). "Whether ADAMTS16/NF-κB/IFI27 regulates EMT, TME, and tumor resistance still needs further study." (PMID 36232317, 2022). "It is believed that IFN-α, induced by IFI27, stimulates myeloid dendritic cells to activate IL-12, which in turn prompts T-cells to secrete IFN-γ, and arms NK cells and CD8+ cytotoxic T lymphocytes (CTL) with perforin A and granzyme B for killing tumor targets." (PMID 23959120, 2013). "Results showed that IFI27, KIF20A, KLK10 and TOP2A were significantly upregulated in tumor cells relative to normal cells, whereas SPINK7 showed no differential expression." (PMID 41008826, 2025). "This “non-basal-like non-classical” tumor subset expresses core signatures such as high TMPRSS4, SLC6A14, IFI27, CST1, and STYK1." (PMID 39774001, 2025). "All tumor cells from the different groups expressed K14, however, we found a lower expression of K14 in TSCC cells induced by the high expression of ATF3, but not in cells with co-expression of ATF3 and IFI6 or IFI27." (PMID 33539340, 2021).
cancer (65 papers, 2013 to 2025). A tumor composed of atypical neoplastic, often pleomorphic cells that invade other tissues. "The overexpression of IFI27 has been linked to drug resistance in cancer and resistance to apoptosis, which allows cancer cells to survive despite chemotherapy." (PMID 39408764, 2024). "The most significantly upregulated gene in D (>1,100‐fold, compared to N) was IFI27, an INFa inducible gene that encodes an intracellular product used as a marker of epithelial‐mesenchymal transition in many forms of cancer." (PMID 31134759, 2019). "IFI27 has been implicated in cancer cell migration, invasion, and poor prognoses." (PMID 38067255, 2023). "The metabolic regulation mediated by IFI27 causes glycolysis deregulation in CD8 T-cells, decreases its number, and aids cancer cells to progress." (PMID 39070493, 2024). "IFI27 has been reported to be involved in the growth of blood vessels by upregulating vascular endothelial growth factor-A (VEGF-A) in cancer cells." (PMID 39070493, 2024). "In the in-situ cancer-1 population, we observed region-specific Interferon-induced expressions, such as IFI27, IFI6, which are associated with cancer growth inhibition and apoptosis promotion." (PMID 35835774, 2022). "We also analyzed the mRNA expression of OAS1 and IFI27 in tissue samples from 26 CRC cancer tissues and 10 normal colon tissues." (PMID 36458816, 2022). "IFI27 expression was higher in cancer tissues than in normal tissues in most cancer types in GEPIA database." (PMID 35346324, 2022). "Next, to reveal if IFI27 is involved in the mechanism of RCAN1–4’s function in cancer cells, migration and invasion assays were performed in RCAN1.4 knockdown SW1990 cells overexpressing IFI27." (PMID 33824473, 2021). "Another interferon alpha inducible protein, IFI27, has been found to be upregulated in some cancers." (PMID 31321241, 2019). "MTT assay was used to detect the effect of -IFI27 knockdown on cell proliferation; Annexin V-PI staining flow cytometry was used to detect the effect of IFI27 downregulation on apoptosis of cancer cells." (PMID 29580248, 2018). "Our study found that in patients with OSCC, the expression of IFI27 was apparently increased in cancer tissues." (PMID 29580248, 2018). "When the expression of IFI27 in those two cancer cell lines was downregulated, the cell proliferation was apparently suppressed compared with the blank control group, according to the MTT results." (PMID 29580248, 2018). "Specifically, NEFH, hepatitis A virus cellular receptor 1 (HAVCR1, 5q33.2), interferon, alpha-inducible protein 27 (IFI27, 14q32), PCSK5, and the arylsulfatase D gene (ARSD, Xp22.3) have been implicated in a variety of cancers." (PMID 28249600, 2017). "Further investigation is necessary to determine the direct link of mitochondrial dysfunction and para-inflammation from IFI27 upregulation with fatigue intensification during cancer therapy." (PMID 23959120, 2013). "Furthermore, emerging evidence suggests broader roles for IFI27 in inflammatory diseases, autoimmune disorders, and cancers." (PMID 41081508, 2025). "IFI27, identified as a proliferation marker in tumors and epithelial cells, plays a role in the progression of various cancers, including cutaneous squamous cell cancer, cholangiocarcinoma, and oral squamous cell carcinoma, and is associated with long-term prognosis 13-15." (PMID 39668835, 2024). "IFI27 downregulation and upregulation in oral squamous cell carcinoma (OSCC) cell lines are linked to an increase and decrease in the percentage of apoptotic cancer cells, respectively, indicating that an upregulation increases cancer cell survival." (PMID 39070493, 2024). "Since IFI6 and IFI27 are downstream targets of activating transcription factor-3 and suppressed to mediate its growth inhibitory actions in cancer cells, it is feasible that the same mechanism mediates the growth inhibitory actions of miR193a-3p in spheroids and needs to be investigated." (PMID 36766731, 2023).
cancer (continued). "Interestingly, miR193a-3p also downregulated the expression of IFI27, an IFNα-inducible oncogenic protein highly expressed in cancer that promotes cell migration by reducing VDGF-A and actin filaments." (PMID 36766731, 2023). "Notably, HLA-I– cancer cells acquiring a mesenchymal status were associated with enhanced mRNA levels of the IFN-stimulated genes IFIT1, IFIT2, IFIT3, IFI6, IFI27, and CCL2." (PMID 35503263, 2022). "Indeed, expression analysis of IFI27 at the TCGA database in our study demonstrated that IFI27 is overexpressed in 24 types of cancer." (PMID 33824473, 2021). "The expression of IFI27 was involved in cancer epithelial cell proliferation." (PMID 34805166, 2021). "This warrants further study of RCAN1.4 and IFI27 as a potential regulatory axis of cancer progression, and targeting this pathway might be a promising therapeutic option for the clinical management of PDAC." (PMID 33824473, 2021). "Importantly, analysis using the Oncomine tool demonstrated that IFI27 is significantly increased in most types of cancer, left)." (PMID 34592906, 2021). "Both IFI6 and IFI27 are type I IFNalpha ISGs, and increasing evidence shows that IFNalpha plays dual opposing roles in cancer development based on ISGs, which determine whether it has anti- or pro-tumorigenic functions." (PMID 33539340, 2021). "Elevated expression of IFI27 in HCT116-CSCs might implicate in their cancer stemness characteristics, particularly tumorigenicity." (PMID 32592372, 2020). "Besides PDPN, many of these molecules, such as IFI6, IFI27, IFI44L, and BOP1, also have been reported to be associated with carcinogenesis and treatment in other types of cancers." (PMID 31321241, 2019). "IFI27 is a hydrophobic mitochondrial protein of 122 amino acids that participates in many biological processes, including apoptosis and innate immunity, which maintains a low expression level in multiple mammalian cells, while it is highly expressed in uterine fibroids and certain cancers." (PMID 33824473, 2021). "When grouped by ZNF536 expression, we found that in the cancer epithelium, ZNF536 exhibited co-expression with PHOX2B and AR, while being excluded from IFI27, IFI6, and ZFP36." (PMID 38720348, 2024). "On the other hand, the expression levels of ISG15, IFI27, OASL, ISG20, and DDX58 were lower in CDDP-R cancer cells than in parent cancer cells, which were consistent with the transcriptome profiling data." (PMID 37174688, 2023). "The RT-qPCR results confirmed that the expressions of ISG15, IFI27, and OASL increased significantly in KU55933-treated CDDP-R and parent cancer cells." (PMID 37174688, 2023). "The results showed that high expressions of ISG15, IFI27, OASL, CCL5, ISG20, IFIT3, and other 21 ISGs were significantly correlated with improved OS rates in cancer patients receiving ICB therapy." (PMID 37174688, 2023). "IFI27, CRYM, HBD, and IFITM3 in TEPs were positively related to the pan‐cancer stage and essential for diagnosing cancers with a sensitivity of 59.1%, 57.8%, 54.3%, and 60.9%, and a specificity of 90.9%, 89.1%, 72.7%, and 94.5%, respectively." (PMID 33955587, 2021). "A slight increase of IFI27, FOXQ1, PRF1, and SLC2A3 genes in CSCs probably implicate in phenotypes of cancer stem cells that were often quiescent, but being able to exhibit their chemoresistant properties." (PMID 32592372, 2020). "IFI27, an interferon alpha-inducible protein, involved in the IFN pathway, was found to be up-regulated in certain cancers, including HCC." (PMID 30138348, 2018). "Importantly, specific representatives of the residual signature genes (ISG15, IFI27, IFI6, RSAD2) appear to aid cancer cells in evading immunosurveillance and inflammatory cells by inhibiting apoptotic processes." (PMID 40312750, 2025).
cancer (continued). "We compared the distribution of patient characteristics: cancer stage, histological grade, sex, and age, partitioned across four sub-groupings based on TGFB2 and IRF9 mRNA expression levels and TGFB2 and IFI27 mRNA expression levels." (PMID 39457004, 2024). "IFI27 (interferon alpha inducible protein 27), a member of the FAM14 family, is stably induced by interferon, and has been reported to regulate biological processes in numerous cancers." (PMID 36232317, 2022). "Furthermore, the results suggest that the anti-cancer activities of tomatidine and TRTLE are mediated by the downregulation of expression of ISGs, such as IFI27." (PMID 35267998, 2022). "Indeed, the expression of CCL8, IFIT1, IFIT3, IFI27, MX1, and RSAD2 has previously been considered favorably prognostic in several types of cancer." (PMID 36180872, 2022). "In this study, 7 TEPs mRNAs were verified, including RSL24D1, IFI27, CRYM, HBD, IFITM3, FCGR2A, and KLHDC8B, which may be used for cancer detection." (PMID 33955587, 2021). "Consequently, we believe alternative TEPs mRNAs, including RSL24D1, IFI27, CRYM, HBD, IFITM3, FCGR2A, and KLHDC8B mRNA, can potentially serve as non‐invasive biomarkers for diagnosing cancers and can even predict the prognosis of pan‐cancer." (PMID 33955587, 2021). "In addition, STAT1/3/5 has been shown to influence ERα in cancer and other diseases and the ISG, IFI27, can directly downregulate ERα expression." (PMID 34680281, 2021). "To clarify whether IFI27 was involved in the migration and invasion of OSCC cancer cells, we used Transwell assay." (PMID 29580248, 2018). "Further study on the interaction between IRF4 and the IFN-inducible genes including IFI27 and IFI44 may disclose the mechanism through which IRF4 confers resistance to IFN treatment of vial cancers by regulating their expression." (PMID 25207815, 2014). "However, the roles of IFI27 and OASL in CDDP-R cancer cells await future investigation." (PMID 37174688, 2023). "Seven TEPs mRNAs were discovered in our study: RSL24D1, IFI27, CRYM, HBD, IFITM3, FCGR2A, and KLHDC8B in TEPs, which are mainly enriched in protein binding, extracellular matrix, and metabolic process, and may be used for cancer diagnosis." (PMID 33955587, 2021).
bacterial infections (24 papers, 2016 to 2025). "Detecting IFI27 mRNA in peripheral blood can differentiate influenza from bacterial infection with an AUC of 0.91, with a sensitivity of 0.80 and a specificity of 0.90." (PMID 39861921, 2025). "A 10-gene panel, including IFI27, distinguishes viral from bacterial infections with an AUC of 0.97, with a sensitivity of 0.93 and a specificity of 0.97." (PMID 39861921, 2025). "IFI27, an interferon-regulated gene, had been proposed as potential marker to distinguish respiratory viral from bacterial infections." (PMID 29947965, 2018). "Still, several differentially expressed genes identified in our study overlapped with those frequently appearing in other published signatures differentiating bacterial from non-bacterial infections developed in immunocompetent children, including IFI27, OASL, and ISG15." (PMID 40806258, 2025). "Human hosts respond to viral and bacterial infections in different ways, the former is characterized by the activation of interferon stimulated genes (ISGs) such as IFI27, while the latter is characterized by the activation of anti-bacterial associated genes (ABGs) such as S100A12." (PMID 36649304, 2023). "IFI27 is a known biomarker of viral vs. bacterial infections connected to IFN signaling." (PMID 34335605, 2021). "In addition, a further 12 ISGs of 380 tested ISGs including STAT1, STAT2, JAK1, IRF9, IRF2, IRF7 are key elements of IFN signaling, and classical and well-known ISGs such as ISG15, PKR, MX1, IFIT1, PML, IFI27 play key roles in viral or bacterial infections." (PMID 30717477, 2019). "After IgAN tonsillectomy, which should eliminate bacterial infection of the tonsils, IFI27 levels might recover to normal levels; consistent with this, the IFI27 level was normal in an IgAN patient who had previously undergone tonsillectomy (patient IgAN25)." (PMID 27100186, 2016). "We showed that the median expression of certain genes (IFI27, HLA-DRB1, USP18, STAP1, and OAS3) in the Biomeme HR-B/V classifier was higher in viral versus bacterial infection." (PMID 41496780, 2025). "When comparing gene expression in viral versus bacterial infection, five classifier genes (OAS3, IFI27, USP18, DSC2, RSP21) were significantly differentially expressed." (PMID 41496780, 2025). "Based on their average logistic regression coefficients, the five most important genes for bacterial classification were CEPT (+), RPGRIP1 (-), FCER1A (-), IFI27 (-), and PDE9A (-), where plus indicates upregulation and minus indicates downregulation for bacterial infection." (PMID 35184750, 2022). "Density plots for the selected genes displayed separate, but overlapping expression patterns with ITGA7, ITGB4 and FAM20A exhibiting higher expression in subjects with bacterial infection and the interferon-related gene IFI27 exhibiting higher expression in subjects lacking a bacterial infection." (PMID 40060038, 2025). "Thus, continuous bacterial infection in the restricted region might suppress IFN-alpha production, resulting in a decrease in IFI27 levels." (PMID 27100186, 2016).
respiratory disease (2 papers, 2021 to 2025). "We compared IFI27 gene expression measured by the InSignia assay to that of the research assay in blood samples collected from patients with respiratory diseases and SARS-CoV-2 vaccinated individuals." (PMID 40593901, 2025). "For example, Echinaforce® treatment increases expression IFI27 and IFITM1, which both play critical roles in antiviral immunity and disease severity in respiratory disease." (PMID 33980308, 2021).